NDRG2 (NDRG family member 2)
Description:
Contributes to the regulation of the Wnt signaling pathway. Down-regulates CTNNB1-mediated transcriptional activation of target genes, such as CCND1, and may thereby act as tumor suppressor. May be involved in dendritic cell and neuron differentiation.
Synonyms: KIAA1248; SYLD
Tractability: Small molecule: a structure with a bound ligand is known. PROTAC: its protein half-life has been measured.
Gene: Protein-coding gene on chromosome 14 (21,016,763 to 21,071,094, reverse strand). Ensembl gene ENSG00000165795.
Subcellular location: Cytoplasm; Cytoplasm, perinuclear region; Cell projection, growth cone
Subcellular location (Human Protein Atlas): Centriolar satellite; Cytosol; Nucleoplasm
Gene Ontology:
Molecular function: protein binding
Biological process: substantia nigra development; signal transduction
Cellular component: cytosol; extracellular exosome; Golgi apparatus; cytoplasm; growth cone; nucleus; perinuclear region of cytoplasm
Genetic constraint (gnomAD): Loss-of-function variants: 32 observed, 56.31 expected, observed/expected ratio (o/e) 0.57, 90% interval 0.43 to 0.76. The upper end of that interval is the gene's LOEUF score, 0.76, which puts it in group 3 of 6, group 1 being the genes least tolerant of losing a copy. Missense variants: 409 observed, 466.82 expected, observed/expected ratio (o/e) 0.88, 90% interval 0.81 to 0.95. Synonymous variants: 181 observed, 176.69 expected, observed/expected ratio (o/e) 1.02, 90% interval 0.91 to 1.16.
Homologues: Orthologues: chimpanzee NDRG2 (99% identical), rabbit NDRG2 (97% identical), dog NDRG2 (96% identical), pig NDRG2 (96% identical), rat Ndrg2 (96% identical), guinea pig NDRG2 (96% identical), mouse Ndrg2 (96% identical), macaque NDRG2 (95% identical), tropical clawed frog ndrg2 (73% identical), zebrafish ndrg2 (69% identical), Drosophila melanogaster MESK2 (37% identical), Caenorhabditis elegans Y48G10A.3 (29% identical), and 2 more. Paralogues in human: NDRG4 (59% identical), NDRG3 (58% identical), NDRG1 (55% identical).
Diseases named in the same sentence as NDRG2 in open-access papers:
NDRG2 is named in the same sentence as 128 diseases in open-access papers, as found by Europe PMC text mining. Sharing a sentence is not in itself a finding about the gene and the disease. The quoted sentences say what the papers report.
breast carcinoma (38 papers, 2010 to 2025). "In the current study, NDRG2 levels were decreased in breast cancer tissues and some cell lines, associated with poor prognosis, and negatively related to miR-181a-5p levels." (PMID 34951340, 2022). "Rescue experiments showed that restoring NDRG2 abolished the effects caused by miR-181a-5p in breast cancer cells." (PMID 34951340, 2022). "But a previous study has reported that NDRG2 is upregulated in basal-like breast cancer and associated with poor prognosis." (PMID 34951340, 2022). "In the present study, it was confirmed that downregulation of NDRG2, which is often observed in several types of cancer patients, is associated with upregulation of PD-L1 expression in breast cancer cells and patients." (PMID 34885221, 2021). "MiR-650 directly targets NDRG2 and its upregulation is inversely associated with decreased NDRG2 expression in colorectal and breast cancer cells." (PMID 31138100, 2019). "Analyzing KMP data showed a favorable RFS (P<0.001) and OS (P = 0.014) in luminal A breast cancer patients with abundant NDRG2 mRNA expression underlining the known tumor suppressive function of NDRG2." (PMID 27400234, 2016). "In patients with IDC abundant NDRG2 mRNA expression showed a significant association (Pearson r: 0.2274, P<0.001) with a high breast cancer 21-gene recurrence score predicting poor prognosis in tamoxifen-treated, node-negative breast cancer." (PMID 27400234, 2016). "We showed a significant (P<0.001) loss of NDRG2 mRNA expression considering all breast cancer subtypes when compared to normal breast tissues (median expression level: 1.3)." (PMID 27400234, 2016). "Underlining the published functional consequences of NDRG2 re-expression in luminal type breast cancer we demonstrated a 26% decreased proliferation rate in NDRG2 over-expressing MCF7 compared to control cells while significance was barely missed (P = 0.064)." (PMID 27400234, 2016). "Unexpectedly, basal-like breast cancer revealed an association of NDRG2 expression with unfavorable patients’ outcome." (PMID 27400234, 2016). "Recent studies investigated promoter hypermethylation as the molecular cause for NDRG2 expression loss in different cancer types including breast cancer." (PMID 27400234, 2016). "NDRG2 has been widely implicated in carcinogenesis including breast cancer invasion, angiogenesis and metastasis." (PMID 27400234, 2016). "With respect to hormone-receptor positive breast cancer (i.e. particularly histological invasive lobular and intrinsic luminal breast carcinoma) these data underline a tumor suppressive role of NDRG2 probably depending on positive hormone-receptor expression." (PMID 27400234, 2016). "Breast cancer patients with low NDRG2 expression had a higher risk of relapse than those with high NDRG2 expression." (PMID 24636131, 2014). "A statistically significant association between long overall survival and high NDRG2 protein levels was found in breast cancer patients." (PMID 24636131, 2014). "The associations between NDRG2 and cancer have been reported in neurologic tumors, gastrointestinal tumors, genitourinary tumors, breast cancer, lung cancer, thyroid cancer, fibrosarcoma, oral squamous-cell carcinoma, myeloid leukemia and cervical cancer (Hela cells)." (PMID 26506239, 2016). "Our data propose a fundamental clinical tumor suppressive role of NDRG2 in hormone-receptor positive breast cancer while in basal-like breast cancer patient’s abundant NDRG2 expression is associated with unfavorable patients’ outcome and a more aggressive phenotype in vitro." (PMID 27400234, 2016). "We correlated NDRG2 loss to the breast cancer subtypes as defined by St." (PMID 27400234, 2016). "Based on hormone-receptor and HER2-negative cancer specimen showing abundant NDRG2 expression, we hypothesized that the described NDRG2 expression loss and thus a putative tumor suppressive function of NDRG2 may be confined to luminal-type breast cancers." (PMID 27400234, 2016).
breast carcinoma (continued). "Of interest, strong (IRS ≥ 6) NDRG2 immunohistochemical staining was significantly associated with low HER2-receptor expression (0–1+) concordant to abundant transcriptional NDRG2 mRNA expression in breast carcinomas with low HER2-expression level." (PMID 27400234, 2016). "Therefore, it is reasonable to assume that the NDRG2-induced reduction in IL-10 signaling may be associated with PD-L1 downregulation in breast cancer cells." (PMID 34885221, 2021). "This is the first study giving evidence that the described putative tumor suppressive function of NDRG2 may be confined to luminal- or basal B-type breast tumors: A more frequently retained NDRG2 mRNA expression associated with unfavorable clinical outcome in basal-type breast cancer patients." (PMID 27400234, 2016). "NDRG2 overexpression in breast cancer (BC) significantly inhibited tumor cell growth by attenuating Janus tyrosine kinases (JAK2) and STAT3 pathways." (PMID 40378957, 2025). "NDRG2 has been reported to be a tumor suppressor and to inhibit glucose uptake in breast cancer cells." (PMID 38611020, 2024). "Two other analyses of large groups of patients with breast cancer have shown that patients with low-NDRG2-expressing tumors had worse disease-free survival or worse overall survival." (PMID 38611020, 2024). "Although most studies have concluded that NDRG2 acts as a tumor suppressor in breast cancer, a single study has described NDRG2 as having both suppressor and promoter functions depending on the subtype of breast cancer." (PMID 38611020, 2024). "Specifically, we observed NDRG1 amplification in 23% of breast cancer samples, whereas NDRG2 was amplified in 0.9% cases, NDRG3 in 2.5% and NDRG4 in 0.3%." (PMID 38611020, 2024). "The decreased expression of N-Myc downstream-regulated gene 2 (NDRG2) in breast cancer can upregulate PD-L1 expression of breast cancer cells and inhibit the proliferation of T cells." (PMID 36624542, 2023). "N-myc downstream-regulated gene 2 (NDRG2) is a tumor suppressor in breast cancer, and its expression is positively correlated with ETS homologous factor (EHF) expression." (PMID 37958443, 2023). "Our previous study revealed that the overexpression of NDRG2 suppressed the migration and invasion of breast cancer cells by repressing the STAT3/Snail signaling pathway, which plays an important role in cell survival, mortality, and proliferation." (PMID 37958443, 2023). "In breast cancer cells, several studies have identified NDRG2 as a tumor suppressor gene, as it is involved in tumor cell proliferation, migration, invasion, and angiogenesis." (PMID 37958443, 2023). "We previously reported that NDRG2 suppresses EMT in breast cancer cells and sought to identify the target genes of NDRG2." (PMID 37958443, 2023). "Collectively, these results suggest that, in TNBC cells, the EHF expression is strongly correlated with NDRG2 expression, which suppresses breast cancer progression." (PMID 37958443, 2023). "In a mouse breast cancer cell model, overexpression of NDRG2 disrupts TGF-β-mediated gene expression and inhibits conversion from latent TGF-β by reducing of integrin β6 expression, which inhibits tumor cell invasion." (PMID 36012631, 2022). "NDRG2 attenuated NF-κB activation in PMA-treated human breast cancer cell (MDA-MB-231), which suppresses migration and invasion by inhibiting COX-2 expression." (PMID 36012631, 2022). "In the current study, we aimed to investigate the levels of miR-181a-5p and NDRG2, and meanwhile explore their role in breast cancer." (PMID 34951340, 2022). "The results indicated that miR-181a-5p levels were upregulated and NDRG2 levels were downregulated in breast cancer, leading to poor prognosis." (PMID 34951340, 2022).
breast carcinoma (continued). "As a tumor suppressor, NDRG2 levels have been proved to be downregulated in numerous types of human cancers, including breast cancer." (PMID 34951340, 2022). "Taking together, overexpression of miR-181a-5p accelerated breast cancer progression through NDRG2-modulated PTEN/AKT pathway." (PMID 34951340, 2022). "MiR-181a-5p targeted NDRG2 to promote the proliferation, invasion and glycolysis of breast cancer cells via regulating the PTEN/AKT pathway." (PMID 34951340, 2022). "In breast cancer, upregulated NDRG2 inhibits cell proliferation, tumor angiogenesis, EMT, glucose uptake, and xenograft tumor growth." (PMID 34951340, 2022). "Past research has also shown that the NDRG2 expression has a significant decrease in gastric, pancreatic, and breast cancers." (PMID 35795037, 2022). "Of note, abnormal expression of NDRG1 or NDRG2 has been found in different cancer types, such as in esophageal cancer, colorectal cancer, breast cancer, prostate cancer, and hepatocellular carcinoma, and is significantly associated with poor prognosis." (PMID 35795037, 2022). "NDRG2 expression was shown to inhibit glucose uptake by promoting the degradation of GLUT1 protein in breast cancer cells." (PMID 34685629, 2021). "In particular, our previous study has shown that NDRG2 expression can inhibit breast cancer development by inhibiting tumor cell proliferation, migration, and epithelial-mesenchymal transition (EMT)." (PMID 34885221, 2021). "The overexpression of NDRG2 in MBA-MB231 breast cancer cells increases SOCS-1 expression, and the JAK/STAT3 pathway is negatively regulated by SOCS-1." (PMID 34685629, 2021). "N-myc downstream-regulated gene 2 (NDRG2) is a candidate tumor suppressor in various cancers, including breast cancer." (PMID 34885221, 2021). "We next investigated The Cancer Genome Atlas (TCGA) datasets to find the correlations among NDRG2, PD-L1, and PD-L2 mRNA expression in human breast cancer patients." (PMID 34885221, 2021). "Collectively, these results unambiguously show that PD-L1 and active forms of STAT3 and NF-κB are strongly expressed in malignant breast cancer cells, but their expression is significantly reduced by NDRG2 overexpression." (PMID 34885221, 2021). "Next, we assessed the effect of NDRG2 overexpression in breast cancer cells on T cell proliferation." (PMID 34885221, 2021). "To verify the effects of NDRG2 overexpression in breast cancer cells, we measured the expression of PD-L1 and PD-L2 by flow cytometry." (PMID 34885221, 2021). "It has been demonstrated the correlations between NDRG2 and cancer within neurotumors, gastroenteric tumors, genitourinary tumors, breast carcinoma, lung carcinoma, thyroid carcinoma, oral squamous-cell cancer, myeloid leukemia, and cervical cancer." (PMID 32345304, 2020). "It has been reported that levels of NDRG2 expression are low in breast cancer cells compared to that in normal tissues." (PMID 32592365, 2020). "NDRG2 has been reported to be reduced within colorectal cancer, liver cancer, thyroid cancer, glioblastoma, breast cancer and a number of other human cancers." (PMID 32345304, 2020). "Transfection of breast carcinoma cells with NDRG2 decreases the expression and proangiogenic activity of HIF1A and VEGF." (PMID 30635008, 2019). "Previous studies showed that overexpression of NDRG2 markedly promoted tumor cell apoptosis in renal cell carcinoma, esophageal carcinoma and breast cancer." (PMID 30348117, 2018). "To assess the contribution of NDRG2 to the apoptosis in drug sensitivity of breast cancer cells, we applied different methods with various mechanisms to evaluate this response." (PMID 28423695, 2017).
breast carcinoma (continued). "In parallel to the abundant NDRG2 expression in basal-type primary breast cancer, we observed a clear tumor suppressive impact mediated by NDRG2 knockdown in metastatic, basal A-like HCC1806." (PMID 27400234, 2016). "Since breast cancer comprises heterogeneous intrinsic subtypes with distinct clinical outcomes we investigated the pivotal role of NDRG2 in basal-type breast cancers." (PMID 27400234, 2016). "In contrast, basal-type breast cancer patients showing abundant NDRG2 expression revealed an unfavorable OS (P = 0.038) and tend to have a worse RFS while significance was barely missed (P = 0.093)." (PMID 27400234, 2016). "Neutralization of BMP-4 in NDRG2-expressing breast cancer cells results in the rescue of MMP9 mRNA expression and migration capacity." (PMID 26506239, 2016). "The current study is the first to analyze in depth NDRG2 expression, as well as its potential clinical and functional impact toward intrinsic breast cancer subtypes." (PMID 27400234, 2016). "Addressing the potentially biological role of NDRG2 in basal-type breast cancer carcinogenesis, the impact of NDRG2 expression on tumor cell proliferation and migration was studied based on our in vitro tumor models." (PMID 27400234, 2016). "Current studies in colon and breast carcinoma revealed that NDRG2 antagonizes transforming growth factor β (TGF-β)–mediated cell invasion." (PMID 27400234, 2016). "Until now, this is the first study investigating the putative role of NDRG2 in depth in basal-type breast cancer." (PMID 27400234, 2016). "NDRG2 expression is negatively correlated with GLUT1 expression in breast carcinoma tissues; NDRG2 promotes GLUT1 protein degradation but does not affect GLUT1 transcription." (PMID 26506239, 2016). "NDRG2 overexpression in malignant breast cancer cells specifically induces the phosphorylation of SAPK and JNK, which contributes to the survival of normal cells and the apoptosis of tumor cells." (PMID 26506239, 2016). "Our tissue collections demonstrated an overall low NDRG2 mRNA expression in breast cancer subtypes compared to normal breast tissue in line with an increased CpG-hypermethylation in breast cancer tissue." (PMID 27400234, 2016). "In vitro, we investigated phenotypic effects caused by NDRG2 silencing in the basal A-like HCC1806 as well as NDRG2 over-expression in basal A-like BT20 compared to luminal-type MCF7 breast cancer cells." (PMID 27400234, 2016). "To address published tumor suppressive function of NDRG2 in luminal-type breast cancer we performed NDRG2 over-expression in luminal MCF7 cells showing low endogenous NDRG2 expression." (PMID 27400234, 2016). "NDRG2, a member of the N-myc downstream-regulated gene family, is thought to be a putative tumor suppressor gene with promising clinical impact in breast cancer." (PMID 27400234, 2016). "So far, NDRG2 was shown to inhibit invasive and metastatic capacity of breast cancer cells by reducing the production of active TGF-β or suppression of MMP-9 activity." (PMID 27400234, 2016). "NDRG2, a member of the N-Myc downstream-regulated gene family, is down-regulated in many human cancers, such as breast cancer, liver cancer, and colorectal cancer, and exerts tumor suppressive functions associated with cell growth, invasion and metastasis." (PMID 25889839, 2015). "NDRG2 also inhibits the metastatic potentials of breast cancer cells through inducing bone morphogenetic protein 4 and subsequent suppression of MMP-9 expression." (PMID 25889839, 2015). "Recently, researchers showed that NDRG2 expression was inversely associated with TNM (tumour, node, metastasis) stage in 189 breast carcinoma tissues and paired normal breast tissues." (PMID 24636131, 2014).